CCL18 (C-C motif chemokine ligand 18)
Diseases named in the same sentence as CCL18 in open-access papers (continued):
Sharing a sentence is not in itself a finding about the gene and the disease.
breast carcinoma (continued). "When CCL18 varied in arm-level gain, the infiltration levels of B cells, CD8 + cells, CD4 + T cells, macrophages and neutrophils decreased significantly in breast cancer samples." (PMID 36805828, 2023). "When CCL18 varied in arm-level gain, the infiltration of B cells, CD8 + cells, CD4 + T cells, macrophages and neutrophils decreased significantly in breast cancer samples." (PMID 36805828, 2023). "These TAMs, in turn, produce elevated levels of CCL18, which induces EMT in breast cancer cells via the phosphatidylinositol 3-kinase (PI3K)/Akt/glycogen synthase kinase 3β (GSK3β)/SNAIL signaling pathway." (PMID 37370762, 2023). "Moreover, CCL18 secreted by tumor-associated macrophages (TAMs) activated a CD10+GPR77+ CAF phenotype in normal breast-resident fibroblasts (NBFs), which could then enrich cancer stem cells (CSCs) and induce chemoresistance in breast cancer cells." (PMID 36418470, 2023). "As a receptor of CCL18, PITPNM3 mainly expressed in human retina, brain, spleen, and breast cancer cells." (PMID 36850011, 2023). "CCL18+ TAM subpopulations can be found in many tumors such as NSCLC, breast cancer, CRCs hepatocellular carcinoma, thyroid cancer and intrahepatic cholangiocarcinoma." (PMID 38347955, 2023). "For example, CCL18 has been shown to increase the proliferation of U-251 GBM cells, MDA-MB-231 and MCF-7 breast cancer cells." (PMID 35955670, 2022). "In breast cancer, HCMV+ TAMs secrete CCL18, which promotes the EMT of breast cancer cells, leading to increased metastasis." (PMID 35847899, 2022). "Since PITPNM3 can be activated by binding with C‐C Motif Chemokine Ligand 18 (CCL18), the relationship between CCL18, PITPNM3 and breast cancer prognosis was determined." (PMID 36285700, 2022). "We previously demonstrated that tumor-associated macrophages (TAMs) can induce EndMT in endothelial cells by secreting CCL18 through the activation of the TGF-β and Notch signaling pathways in breast cancer." (PMID 36465358, 2022). "In addition, while CCL18 promoted the invasion and metastasis of breast cancer, the suppression of PITPNM3 abolished these effects, what may confirm the critical role of TAM-derived CCL18 in promoting breast cancer metastasis via its atypical chemokine receptor, PITPNM3." (PMID 32456359, 2020). "TREM2hi macrophages had been reported in a breast cancer single-cell study to be a branch of recruited or resident M2 type macrophages expressing several genes in common with our study such as SSP1, C1Q, CCL18, and MACRO50." (PMID 33033253, 2020). "An in vitro study further illustrated the role of CCL18 in promoting angiogenesis and tumor migration in breast cancer, as TAM’s involvement in mediating angiogenesis was diminished by blocking CCL18 and CCL18 receptors." (PMID 31952335, 2020). "Here we delineate that CCL-18 and VEGF enhance breast cancer migration and invasion, potentially as a pre-angiogenic step." (PMID 31214501, 2019). "A recent study demonstrated that the CCL18-mediated down-regulation of miR-98 enhanced the EMT of breast cancer cells, and thus promoted breast cancer metastasis." (PMID 29989015, 2018). "CCL-18 is a key factor secreted by TAMs to induce cancer cell epithelial-mesenchymal transition (EMT), enhance breast cancer metastasis, and reduce patient survival." (PMID 30618757, 2018). "CCL18 and GM‐CSF expression are correlated (a) with each other and (b) with EMT‐like features in human breast cancer specimens, and GM‐CSF expression predicts a shorter DFS." (PMID 28599100, 2017). "Our results suggest that Tregs in human breast cancer are mainly converted from naive PB CD4+ T cells, recruited by TAM-derived CCL18." (PMID 28290464, 2017). "Previous studies reported that CCL18-PITPNM3 binding induces Pyk2/Src or PI3K/Akt/GSK3β/Snail signaling and the subsequent metastasis of breast cancer." (PMID 26919103, 2016). "Therefore, retrieving miR98 expression could inhibit CCL18-induced EMT in breast cancer cells." (PMID 26244871, 2015).
breast carcinoma (continued). "A positive feedback loop between CCL18 pathway and miR98 down-regulation was then formed to maintain EMT and promote migration and invasion of breast cancer cells." (PMID 26244871, 2015). "In agreement, our present study indicates that CCL18-induced miR27b reduction in both MDA-MB-231 and MCF-7 cells promotes breast cancer invasion and migration." (PMID 26244871, 2015). "In summary, our study shows that CCL18, an important TAM-derived cytokine, can repress the expression of miR98 and miR27b in breast cancer cells." (PMID 26244871, 2015). "Our previous data revealed that CCL18 promotes extracellular matrix adherence and breast cancer cell invasion by binding to its potential cognate surface receptor PITPNM3, whose expression is essential for CCL18-induced calcium influx and chemotaxis." (PMID 26416449, 2015). "After exposure to CCL18 for 12 hr, the N-Ras/ERK/PI3K/AKT signaling pathway in breast cancer cells is activated and triggers activation of NFκB, which is the central mediator for the maintenance of EMT in vivo and in vitro." (PMID 26244871, 2015). "Similarly, CCL18, a TAM-secreted chemokine, activates JAK2/STAT3 signaling in ESCA, correlating with poor prognosis, as seen in ovarian and breast cancers." (PMID 40134607, 2025). "In parallel, immunostaining showed that the proportion of ALDH1+ breast cancer cells was considerably higher in the xenografts formed by MCF-7 cells coinjected with NBFs and treated with CCL18, and the mice harboring these tumors also had a greater abundance of CD10+GRP77+ fibroblasts." (PMID 36418470, 2023). "In agreement with previous data, the proportions of CD44+CD24- and ALDH1+ breast CSCs were dramatically increased among breast cancer cells cocultured with CCL18-activated NBFs but not with treatment-naive or TGF-β-treated NBFs." (PMID 36418470, 2023). "As reported, CCL18 could promote the migration, invasion, EMT and metastasis of the breast cancer and hepatocellular carcinoma cells through the phosphorylation of PyK2 or NF-κB signaling pathway." (PMID 36850011, 2023). "The CCL18 could recruit CD4+CD45RA+CD25- naïve T cells into the tumor niche, and then differentiated into Treg cells, as shown in gastric cancer and breast cancer." (PMID 38347955, 2023). "CCL18 and TRGC1 were highly correlated with survival outcome in breast cancer patients." (PMID 36805828, 2023). "In addition, CCL18-induced increases in breast cancer cell (MDA-MB-231) migration, accompanied by the activation of PyK2 and Src, whereas CCL18-induced cell migration was attenuated by siRNA-PyK2 and siRNA-Src." (PMID 36555115, 2022). "We also demonstrated that the absence of clinical response in patients with breast cancer after anthracycline-containing NAC correlated with M2+ macrophage phenotype (YKL−39−CCL18+ or YKL−39+CCL18−)." (PMID 34209679, 2021). "In addition, in tumour tissue the TAM-like phenotype of macrophages activated by mesenchymal-type breast cancer cells will, in turn, produce CCL18 to induce EMT of cancer cells, forming a positive feedback loop and promoting breast cancer metastasis." (PMID 34187256, 2021). "Furthermore, the positive feedback loop between GM-CSF secreted from breast cancer cells and CCL18 from M2-TAMs facilitates EMT process, induces tumor progression and reduces the patient’s survival in breast cancer." (PMID 33129234, 2021). "In addition, CCL18-producing TAMs also promoted in vitro human umbilical vein endothelial cell (HUVEC) migration and tube formation, tumor angiogenesis, and EMT of breast cancer cells via its receptor PITPNM3." (PMID 34503058, 2021). "The CCL18 chemokine recruits CD4+CD45RA+CD25- naïve T cells into the tumor niche, and then they are differentiated into Treg cells, as shown in research studies on gastric cancer and breast cancer." (PMID 33114763, 2020). "Currently, no experimental work examining CCL18 as a therapeutic target in cancer other than breast cancer is available." (PMID 33114763, 2020).
breast carcinoma (continued). "In vivo studies on NOD/SCID mice inoculated with MDA-MB-231 breast cancer cells showed that blocking CCL18 activity does not affect tumor growth or metastasis to the lungs." (PMID 33114763, 2020). "Furthermore, CCL18 secreted by TAM has previously been reported to promote angiogenesis and metastasis formation in breast cancer, consistent with our findings for HGSOC." (PMID 29141914, 2018). "In addition, TAMs produce CCL18; binding of CCL18 to its specific receptor PITPNM family member 3 (PITPNM3) facilitates breast cancer metastasis through activation of intracellular calcium signal." (PMID 28356139, 2017). "PITPNM3 overexpression was reported in breast cancer tissue and cancer cell lines, independent of the CCL18+ TAM counts." (PMID 26919103, 2016). "Both CCL18 and MCP-1 can promote breast cancer progression in human." (PMID 26834744, 2016). "In breast cancers, it was reported that cancer cells activated macrophages to a TAM-like phenotype by producing GM-CSF, and reciprocally, CCL18 released from TAMs induced the epithelial mesenchymal transition (EMT) of breast cancer cells, thus forming a positive feedback loop." (PMID 27888616, 2016). "After treatment with CCL18, the N-Ras/ERK/PI3K/NFκB/Lin28b pathway was consistently active, which was maintained by down-regulation of miR98 and miR27b, leading to EMT of epithelial breast cancer cells." (PMID 26244871, 2015). "CCL18 treatment for 6 or 8 hr enhanced the migration and invasion of breast cancer cells that were transfected with a negative control or mock-transfected by 4- and 3-fold, respectively (Figure SF, SG)." (PMID 26244871, 2015). "Moreover, down-regulation of miR98 and miR27b maintains the activation of CCL18 signaling and promotes EMT and invasiveness of breast cancer cells." (PMID 26244871, 2015). "In addition, CCL18 can bind with PITPNM3, inducing EMT, migration, and invasion of non-small cell lung cancer and breast cancer via PI3K/Akt/GSK3β/Snail signaling pathway and engulfment and cell motility 1/dedicator of cytokinesis protein 4 CRK binding protein signaling pathway, respectively." (PMID 35609322, 2022). "After quantitative calculation, the levels of serum CCL18 and CXCL1 antigens, and C1D, TM4SF1, FXR1, and ZNF573 IgG autoantibodies were significantly higher in patients with OC than in those with cervical cancer, liver cancer, breast cancer, gynecological benign tumor patients, and healthy women." (PMID 34995016, 2022). "Although the CCL18-PITPNM3 signaling pathway has not been revealed to play a role in bone metastasis of breast cancer, it remains unknown whether the anti-CCL18 antibody could be utilized for the treatment of breast cancer with bone metastasis." (PMID 33435254, 2021). "Our results were in accordance with previous study, which comprehensively demonstrated that CCL18+ TAMs infiltration in the tumor invasive front might establish an aggressive TME and could regulate breast cancer cells an EMT shift to increase metastatic ability." (PMID 30927925, 2019). "Recently, mesenchymal-like human breast cancer cells were demonstrated to produce GM-CSF and cancer cell-derived GM-CSF transformed macrophages to a TAM-like phenotype and to produce the chemokine CCL18, promoting the lung and liver metastasis in humanized mice." (PMID 31888216, 2019). "For example, mesenchymal-like breast cancer cells secrete granulocyte–macrophage colony-stimulating factor to promote TAM recruitment, but CCL18 secreted by TAMs may activate the cancer cell EMT program, creating a positive feedback loop between stromal macrophages and cancer cells." (PMID 30158589, 2018). "In turn, chemokine CCL18 secreted by TAMs induces mesenchymal-like breast cancer cells to activate the EMT program, thus creating a positive feedback loop between macrophages and mesenchymal-like breast cancer cells to promote invasion and metastasis of breast cancer cells." (PMID 28356139, 2017).
breast carcinoma (continued). "Recently, mesenchymal-like human breast cancer cells were demonstrated to produce GM-CSF and cancer cell-derived GM-CSF transformed macrophages to a TAM-like phenotype and to produce the chemokine CCL18, leading to the promotion of metastasis to the lung and liver in humanized mice." (PMID 26834744, 2016). "The understanding of CCL18 function has been hampered until the recent identification of PITPNM3 (phosphatidylinositol transfer protein 3; also named PYK2 N-terminal domain interacting receptor 1, Nir1) in breast cancer, which has a high binding affinity for CCL18." (PMID 26919103, 2016). "To further investigate whether the integrated N-Ras/ERK/PI3K/NFκB/Lin28b signaling pathway was essential for the repression of miR98 by CCL18, we transfected siRNAs targeting N-Ras or Lin28b mRNA into MCF-7 breast cancer cells, which were then exposed to CCL18 (20 ng/ml) for 48 hr." (PMID 26244871, 2015). "To evaluate whether miR98 reduction contributes to CCL18 enhanced breast cancer metastasis in vivo, we inoculated MDA-MB-231 breast cancer cells that were infected with lentivirus carrying NC or miR98 and stimulated by CCL18 (20 ng/ml) for 14 d into the mammary fat pads of nude mice." (PMID 26244871, 2015). "Thus, CCL18 and/or its potential receptor PITPNM3 may serve as therapeutic targets for inhibiting angiogenesis in breast cancer, particularly for patients with resistance to anti-VEGF monotherapy." (PMID 26416449, 2015). "Indeed, conditioned media from mesenchymal‐like breast cancer cell lines activate macrophages into a TAM‐like phenotype, including high expression of CD206 (a scavenger receptor also known as macrophage mannose receptor or MMR) and high secretion of CCL17, CCL18, CCL22, and IL‐10." (PMID 28599100, 2017). "Thus CCL18 expressed by TAMs selectively recruits circulating naive CD4+ T cells, but not memory or Treg CD4+ T cells, into breast cancer." (PMID 28290464, 2017). "Since CCL18 is absent in mice, it is plausible that MCP-1 may act as a chemokine counterpart of human CCL18 for breast cancer progression in mice." (PMID 26834744, 2016). "Interestingly, immunofluorescence staining showed that the reduced E-cadherin and increased vimentin, which were induced by CCL18 as previously reported, were alleviated in the MCF-7 breast cancer cells transfected with miR98 mimics, but not with irrelevant negative controls." (PMID 26244871, 2015). "Although CCL18 induces the increased vimentin and decreased E-cadherin, as well as the upregulation of GM-CSF, IL-8, CCL2, and GRO, the upregulated levels of IL-8 in breast cancer cell might be not enough to induce the enrichment of cancer stem cell and mediate chemoresistance." (PMID 36418470, 2023).
pulmonary fibrosis (53 papers, 2010 to 2025). Chronic progressive interstitial lung disorder characterized by the replacement of the lung tissue by connective tissue, leading to progressive dyspnea, respiratory failure, or right heart failure. "Clinical studies have demonstrated that CCL18 serves as an important biomarker for assessing the progression of pulmonary fibrosis, with elevated levels closely associated with disease severity." (PMID 39910395, 2025). "CCL18 has been suggested as a marker for identifying patients at a higher risk of developing pulmonary fibrosis or progressive disease." (PMID 41279897, 2025). "Chemokines, such as CXCL12, CCL1, and CCL18, are implicated in pulmonary fibrosis, acting as chemoattractants by combining with the chemokine receptors, and yet the role of CXCL16 and its receptor remain poorly understood." (PMID 38789926, 2024). "CCL18 supports a M2 polarization of macrophages in sarcoidosis-associated pulmonary fibrosis and suggests a pathogenic role of these macrophages in the fibrotic response." (PMID 36148463, 2022). "High levels of CCL18 are directly linked to the increased matrix deposition in pulmonary fibrosis." (PMID 38334630, 2024). "Higher levels of PARC (also known as CCL18) have been previously associated with an increased risk of death in patients with a range of chronic diseases, including chronic obstructive pulmonary disease, idiopathic pulmonary fibrosis, coronary artery disease, and cancer progression." (PMID 37803875, 2023). "In pulmonary fibrosis, serum levels of CCL18 are significantly higher in patients compared to healthy controls." (PMID 39910395, 2025). "Elevated serum levels of CCL18 have been consistently reported in patients with pulmonary fibrosis, with studies demonstrating a correlation between serum concentrations and the extent of fibrotic activity." (PMID 41301749, 2025). "In pulmonary fibrosis, alveolar macrophages play a major role in the production of C-C motif chemokine ligand 18 (CCL18), which contributes to the development of the disease." (PMID 40843700, 2025). "We found elevated CCL18 serum levels and increased CCL18 release by alveolar macrophages from patients suffering from pulmonary fibrosis." (PMID 38334630, 2024). "The only independent predictors of lung fibrosis progression in Model 2 were high CCL18 serum levels (OR 1.009 [95% CI 1.003–1.015], p = 0.004) and positive antisynthetase autoantibodies (OR 5.075 [95% CI 1.120–22.999], p = 0.035)." (PMID 37238199, 2023). "Circulating CCL18 serum levels correlated with the severity of fibrosis in idiopathic pulmonary fibrosis (IPF) and can predict ILD progression in systemic sclerosis (SSc)." (PMID 37238199, 2023). "Human alveolar macrophages were found to overexpress CC chemokine ligand 18 (CCL18) in patients with pulmonary fibrosis and CCL18 production was negatively correlated with pulmonary function tests." (PMID 37630598, 2023). "In pulmonary fibrosis, fibrosis-related factors such as chemokines (IL-8, CCL18), proteases (MMP-1, MMP-7) or growth factors have been suggested to have diagnostic potential for fibrosis, but their utility in clinical routine has not been established." (PMID 37814303, 2023). "It has been demonstrated that increased CCL18 levels are predictive of mortality and pulmonary fibrosis progression in patients with IPF and SSc." (PMID 37238199, 2023). "Apart from IPF, elevated serum CCL18 levels reflected pulmonary fibrosis activity and correlated with death or the progression of pulmonary disease in patients with systemic sclerosis (SSc)-associated ILD." (PMID 32575869, 2020). "Spontaneous production of CCL18 by BAL cells of patients with pulmonary fibrosis.Supernatants from AMs of patients containing CCL18 induce collagen production by normal lung fibroblasts." (PMID 28507549, 2017). "In the setting of pulmonary fibrosis, alveolar macrophages are believed to be the main source of CCL18 in the lung and play a role in the pathogenesis of pulmonary fibrosis." (PMID 28353114, 2017).